APOB (apolipoprotein B)
Diseases named in the same sentence as APOB in open-access papers (continued):
Sharing a sentence is not in itself a finding about the gene and the disease.
cardiovascular disease (continued). "The 2012 European Guidelines for the prevention of cardiovascular diseases recommend the use of non-HDL-C as a parameter to quantify the amount of atherogenic lipoproteins containing apolipoprotein B, which allows the prediction of CVD risk to a similar extent or even more accurately than LDL-C." (PMID 25024747, 2014). "It is important to determine whether adding information on apolipoprotein B (apoB) and apolipoprotein A1 (apoA1), lipoprotein (a) or lipoprotein-associated phospholipase A2 to total cholesterol (TC), LDL-C and HDL-C improves cardiovascular disease (CVD) risk prediction." (PMID 24573394, 2014). "The ratio of two apolipoproteins with distinct functions, Apolipoprotein B/Apolipoprotein A1 (APOB/APOA1), has been proposed as a novel assessment index for the evaluation of cardiovascular diseases." (PMID 40787622, 2025). "APOB/APOA1, as a novel lipid parameter, shows a unique clinical value in the field of cardiovascular disease." (PMID 40787622, 2025). "Apolipoprotein B (ApoB) is the main lipoprotein in LDL-C and a biomarker for cardiovascular diseases and has been evaluated in a previous study." (PMID 39767734, 2024). "Generally, low-density lipoprotein (LDL) particle size can be inferred from the LDL cholesterol concentration to total apolipoprotein B concentration ratio (LDL-C/ApoB ratio, hereinafter called LAR), which is a good predictor of cardiovascular disease." (PMID 37480052, 2023). "It should be noted that the association described in our work was predominant in those molecules whose elevation is considered deleterious in terms of cardiovascular disease (total cholesterol, LDL cholesterol, apolipoprotein B, and atherogenic index)." (PMID 37759971, 2023). "Apolipoprotein B (Apo B) is the major component of LDL and has been well-studied with regard to cardiovascular diseases." (PMID 34825306, 2022). "The lipid homeostasis system is covered by more than 20 factors, several of which—including apolipoprotein A1 (APOA1), apolipoprotein B (APOB), and apolipoprotein(a) (LPA)—are important predictors of cardiovascular diseases." (PMID 33444735, 2021). "Nevertheless, we demonstrated here that TNFα-induced EC inflammation is reduced by apoB-depleted plasma similarly to HDL isolated by ultracentrifugation, which is of interest for investigators studying cardiovascular disease." (PMID 30678190, 2019). "Routine apolipoprotein (apo) measurements for cardiovascular disease (CVD) are restricted to apoA-I and apoB." (PMID 28209220, 2017). "The intake of polyunsaturated fatty acids was inversely correlated with apolipoprotein B (Apo-B), the main apolipoprotein of LDL-cholesterol and a marker of cardiovascular disease (rho = −0.17, p = 0.046)." (PMID 26574072, 2015). "A majorlimitation in studying the relationship between ApoB and BMD is thathyperlipidemia often coexists with conditions that may affect bone health, suchas cardiovascular diseases." (PMID 40475729, 2025). "Several new markers have been introduced as alternative means to refine risk estimation beyond LDL-c in the presence of cardiovascular disease, such as non-HDL-c, TC/HDL-c ratio, and the apoB/apoA1 ratio." (PMID 38443803, 2024). "Previous Mendelian randomization studies and discordance analyses have further determined that apoB is more accurate as a marker of coronary calcification and cardiovascular disease than LDL-c or non-HDL-c." (PMID 36369093, 2022). "In patients affected by cardiovascular diseases and in healthy controls, the LDL-C/apoB ratio, the apoB/TG ratio, and the LDL isoelectric point (i.e., surface charge) can predict the ex vivo complex formation of LDL with arterial PGs (LDL-PG affinity) with 70% accuracy." (PMID 33713671, 2021). "Evolocumab Q2W or QM enabled most individuals at high/very-high cardiovascular disease risk to achieve their LDL-C, non-HDL-C, and ApoB recommended goals." (PMID 33941192, 2021).
cardiovascular disease (continued). "Many studies have suggested that ApoB is a more accurate marker of cardiovascular disease than LDL-C or non-HDL-C." (PMID 33967959, 2021). "Lowering apolipoprotein B secretion from HepG2 cells and decreasing the level of low-density lipoprotein (LDL)-cholesterol oxidation are mechanisms related to the prevention of cardiovascular diseases (CVD)." (PMID 31146372, 2019). "It should be noted that the primary endpoints of the included studies were cardiovascular disease, LDL-cholesterol levels, HDL-cholesterol levels, or other outcomes such as serum triglyceride levels, apolipoprotein B, serum dehydroepiandrosterone sulfate levels, and C-reactive protein levels." (PMID 30425742, 2018). "Non-HDL-cholesterol and ApoB have been described as more useful markers for the prediction of cardiovascular disease." (PMID 26398887, 2015). "Although many studies have demonstrated the importance of the apoB/apoA-I ratio in predicting the presence or absence of cardiovascular disease, less is known about apoB/apoA-I ratio as a marker of plasma atherogenicity." (PMID 25852220, 2015). "Background/Objectives: While the benefits of almond consumption in reducing levels of TC and LDL-C are well established, the effects on additional lipids that have emerged as important predictors of cardiovascular disease, such as ApoB and the ratio of ApoB:ApoA, are not well characterized." (PMID 40944180, 2025). "However, limited research exists on the impact of serum apolipoprotein B (ApoB) on bone mineral density (BMD); meanwhile, it remains unclear to what extent cardiovascular disease plays in mediating this process." (PMID 40475729, 2025). "Therefore, CETP inhibitors may be promising for the prevention of cardiovascular disease, since they increase HDL and decrease LDL and ApoB." (PMID 36986146, 2023). "Apolipoprotein B (apoB) and non-high-density lipoprotein cholesterol (non-HDL-C) have been shown to predict cardiovascular disease (CVD) even in the case of low levels of low-density lipoprotein cholesterol (LDL-C)." (PMID 35665267, 2022). "Several new markers have been introduced as alternative means to refine risk estimation beyond LDL-c from Friedewald’s formula in the presence of cardiovascular disease, such as non-HDL cholesterol, total cholesterol/HDL-c ratio, non-HDL cholesterol/HDL-c, and the apoB/apoA1 ratio." (PMID 31744496, 2019).
cancer (135 papers, 2011 to 2026). A tumor composed of atypical neoplastic, often pleomorphic cells that invade other tissues. "This study's aim was to clarify the regulatory roles of the MKI67 rs11016073 and APOB rs1367117 polymorphisms in the relationship between blood Pb levels and cancer risk." (PMID 41828541, 2026). "The loss of this modified APOB proteoform in cancer patients underscores how PTM-defined proteoforms can distinguish health from disease within the plasma corona." (PMID 41001529, 2025). "This SH-SAW sensor demonstrated the capability to detect biological markers, including C-reactive protein (CRP), lipoprotein (a) (Lp(a)), and apolipoprotein B (ApoB), which are associated with inflammatory processes linked to cancer." (PMID 39996991, 2025). "For example, mutation signatures SBS2 and SBS13 are associated with the activation of APOBEC (Apolipoprotein B mRNA editing enzyme, catalytic polypeptide), a major driver of subclonal evolution of the cancer genome." (PMID 38297116, 2024). "This discrepancy underscores the importance of considering cancer type, patient demographics, and potential confounding factors when interpreting ApoB’s role in cancer risk and prognosis." (PMID 39193372, 2024). "High levels of LDL‐C and apoB have been linked to an increased incidence of cancer and metastasis in most cancers." (PMID 38819098, 2024). "In approximately 75% of cancer types and about 50% of all cancers analyzed, mutations associated with the apolipoprotein B mRNA-editing enzyme catalytic polypeptide (APOBEC; A) represent one of the most common endogenous mutational mechanisms in cancer." (PMID 39336718, 2024). "Some studies report that the ApoB/ApoA1 ratio is associated with the increase of overall cancer incidence in males." (PMID 39252808, 2024). "The loss of APOB expression in several types of cancers is also associated with the upregulation of oncogenes and poor prognosis." (PMID 38283944, 2023). "In HCC, APOB can be altered by somatic mutations or hypermethylation, resulting in the diverting of energy to cancer metabolic pathways." (PMID 37628784, 2023). "Both had high tumor mutational burden (TMB-H) with Catalogue of Somatic Mutations in Cancer (COSMIC) mutational signatures associated with apolipoprotein B mRNA-editing enzyme catalytic polypeptide (APOBEC) and ultraviolet (UV) light, respectively." (PMID 37277454, 2023). "Apolipoprotein B mRNA editing enzyme-catalyzed polypeptide-like (APOBEC)-induced mutations across the cancer genome are common and correlated with the levels of APOBEC mRNA." (PMID 35510248, 2022). "Cytidine deaminases activity causes instability and cancer in the human genome, and apolipoprotein B mRNA editing enzyme catalytic subunit 3A (APOBEC3A) is by far the most active member of this family." (PMID 36497451, 2022). "APOBEC (apolipoprotein B mRNA editing enzyme, catalytic polypeptide-like) and DNA repair defects are mutational drivers that are signatures for hypermutated cancer." (PMID 34503126, 2021). "In the fully adjusted model, participants in the highest quartile (Q4) of apoB/apoA-I had a significantly greater risk for cancer mortality (hazard ratio (HR): 1.40; 95% confidence interval (CI): 1.25–1.93) compared with those in the first quartile (Q1)." (PMID 31936330, 2020). "The association of apoB with cancer is far less clear, since apoB studies have mostly focused on cardiometabolic disorders." (PMID 31936330, 2020). "Apolipoprotein B mRNA-editing enzyme catalytic polypeptide-like 3 (APOBEC3) family of enzymes are endogenous sources of somatic mutations found in multiple human cancers." (PMID 33292100, 2020). "Previous results from the Malmö Diet and Cancer Study have shown a weak association between intake of sugar-sweetened foods and drinks and ApoB/ApoA." (PMID 33425973, 2020).
cancer (continued). "In conclusion, in the large representative samples of the US adult population, the apoB/apoA-I ratio and apoB levels significantly predicted cancer mortality, independently of several cardiometabolic risk factors." (PMID 31936330, 2020). "Based on the obtained results, we showed that apoB/apoA-I ratio was significantly associated with cancer mortality, independently of other cardiometabolic risk factors." (PMID 31936330, 2020). "By using two nationally representative samples of US adults, we prospectively evaluated the associations between apolipoprotein B (apoB) levels and apoB/apoA-I ratio with cancer mortality." (PMID 31936330, 2020). "In the same model, a positive and significant association between apoB levels and cancer mortality was observed for individuals in Q3 (HR: 1.12; 95% CI: 1.09–1.16) and Q4 (HR: 1.17; 95% CI: 1.09–1.25) compared with those in Q1." (PMID 31936330, 2020). "They found that a decreased ApoB/ApoA-I was associated with improved cancer-specific survival and OS." (PMID 31956353, 2020). "Apolipoprotein B mRNA-editing enzyme catalytic polypeptide-like (APOBEC) DNA cytosine deaminases have emerged as potential genomic mutators in various cancers." (PMID 31073151, 2019). "They found that mutation of APOB was associated with switching on of cancer-promoting genes, and switching off of genes that suppress tumor growth." (PMID 30429453, 2018). "The apolipoprotein B mRNA editing catalytic polypeptide-like (APOBEC) mutation signature in particular is very common in HPV-positive cancers, likely triggered by the host response to HPV infection." (PMID 28771191, 2017). "Recent genome-wide sequencing data showed that apolipoprotein B mRNA editing catalytic polypeptide-like 3B (APOBEC3B) is a key molecular driver inducing mutations in multiple human cancers." (PMID 28572915, 2017). "Apolipoprotein B (APOB), a key structural component of plasma lipoproteins involved in lipid metabolism and transport, has recently been implicated in the onset of various human cancers." (PMID 39979869, 2025). "It is hypothesised that mutations that render apolipoprotein B inactive are preferred in tumorigenesis in order to provide more energy for cancer metabolism." (PMID 38263244, 2024). "The observation that ApoB may have opposing effects on cancer risk depending on the cancer type and patient gender further complicates the picture." (PMID 39193372, 2024). "However, other studies showed that the downregulation of APOB was correlated with an increased risk of cancer." (PMID 38067270, 2023). "In addition, it was found that APOB has varying genotype expression in different cancers, with some genotypes associated with favorable outcomes and others resulting in inferior survival rates in NSCLC." (PMID 38067270, 2023). "Due to the high expression of ALB (20%) and APOB’s ability to facilitate VLDL secretion (which consumes large amounts of energy), mutation of ALB or APOB may be inactivated to divert energy into cancer-relevant metabolic pathways." (PMID 36881382, 2023). "However, the exact mechanism by which 4HNE association with apoB affects cancer growth at the early vs later stages has to be elucidated." (PMID 36864816, 2023). "It is speculated that APOB inactivating mutation is preferred in tumorigenesis to provide more energy to cancer metabolism because much energy is required to form VLDL with ApoB-100, a isoform of ApoB." (PMID 36506554, 2022). "Notably, among various mutational signatures, the APOBEC (apolipoprotein B mRNA editing enzyme, catalytic polypeptide-like) family contributes a major source of the DNA modification in cancer genome, showing a specific mutational pattern: APOBEC mutagenesis." (PMID 35673559, 2022). "ApoB-lipoproteins and their components modulate intracellular metabolism and have been associated with the development of neoplastic phenomena, such as proliferation, anchorage-independent growth, epithelial-mesenchymal transition, and cancer invasion." (PMID 34093831, 2021).
cancer (continued). "APOB caused a high mutation burden of cancer genes and tumorigenesis." (PMID 33509222, 2021). "For future studies, it would be important to look at each cancer type separately, since different types of malignancies may have a varied association with apoB or apoA levels." (PMID 31936330, 2020). "We found that individuals with higher apoB/apoA-I ratio and apoB levels might have a greater cancer mortality risk." (PMID 31936330, 2020). "Large-scale analysis of mutational signatures across human cancers strongly suggest that dysregulated deamination of DNA cytosine to uracil by the apolipoprotein B mRNA editing enzyme, catalytic polypeptide-like (APOBEC)/AID family of deaminases plays an important role in tumorigenesis." (PMID 32264925, 2020). "While ApoB's research focuses on cardiac metabolic disorders, the study found that individuals with higher ApoB levels might have a greater cancer mortality risk." (PMID 32391278, 2020). "The associations of apoB levels with cancer have been previously evaluated." (PMID 31936330, 2020). "If further evidence supports our findings, apoA-I and apoB measurements may be considered in general healthcare policies, especially for those at high risk of cancer development." (PMID 31936330, 2020). "Because such a large amount of energy is required to form very low-density lipoprotein, it can be speculated that APOB-inactivating mutations may be selected during carcinogenesis to divert energy into cancer-related metabolic pathways." (PMID 30429453, 2018). "Cancer genome sequencing has implicated the cytosine deaminase activity of apolipoprotein B mRNA editing enzyme catalytic polypeptide-like (APOBEC) genes as an important source of mutations in diverse cancers, with APOBEC3B (A3B) expression especially correlated with such cancer mutations." (PMID 28977491, 2017). "This type of clustered mutations and mutation ‘showers’ have recently been shown to be functionally linked with cancer development through the action of APOBEC (apolipoprotein B mRNA-editing enzyme, catalytic polypeptide-like) cytidine deaminases, especially APOBEC3B." (PMID 24244712, 2013). "Its only confirmed physiologic target is the apolipoprotein B (APOB) mRNA, though it can also deaminate DNA, a process linked to cancer." (PMID 40356722, 2025). "APOBEC3s, members of the Apolipoprotein B mRNA-editing enzyme catalytic polypeptides (APOBECs) superfamily, exhibit overexpression across various cancer types, notably bladder and prostate cancer." (PMID 39910169, 2025). "In this study, we found the glycopeptides of APOB were abundant in patients with PDAC compared to cancer-free controls." (PMID 38029961, 2024). "Patients with the ε2 allele in LUAD exhibited disrupted lipid metabolism, characterized by reduced HDL, TC, and FFA levels, along with increased ApoB, particularly in advanced and poorly differentiated cancer stages." (PMID 39763652, 2024). "Two APOBEC (apolipoprotein-B mRNA editing enzyme catalytic polypeptide-like) DNA cytosine deaminase enzymes (APOBEC3A and APOBEC3B) generate somatic mutations in cancer, driving tumour development and drug resistance." (PMID 38496447, 2024). "It is worth noting that previous research has shown a connection between APOB and diverse forms of cancer, such as gallbladder cancer, low-grade glioma, non-small cell lung cancer, and primary small cell carcinoma of the esophagus." (PMID 38310202, 2024). "Within individuals devoid of cancer, we explore the linear relationship between serum TT and apoB in various CVD." (PMID 38435750, 2024). "Apolipoprotein B messenger RNA (mRNA) editing enzyme, catalytic polypeptide-like (APOBEC) cytidine deaminases cause genetic instability during cancer development." (PMID 38155930, 2023). "Although the link between apoB and 4HNE has been previously shown, the significance of apoB and 4HNE in cancer development remains to be elucidated." (PMID 36864816, 2023).